PTX3 (pentraxin 3)
Diseases named in the same sentence as PTX3 in open-access papers (continued):
Sharing a sentence is not in itself a finding about the gene and the disease.
PTX3 also shares sentences with these, for which no sentence is quoted: idiopathic pulmonary fibrosis (8 papers); liposarcoma (7); chronic periodontitis (6); congestive heart failure (4); end-stage renal disease (4); nonalcoholic steatohepatitis (4); skin carcinoma (4); acute myeloid leukemia (3); airway hyperresponsiveness (3); cardiac arrest (3); nonalcoholic fatty liver disease (3); polymyalgia rheumatica (3); psoriatic arthritis (3); renal cell carcinoma (3); abdominal aortic aneurysm (2); Allergy (2); atypical hemolytic-uremic syndrome (2); central nervous system infections (2); depression (2); epileptic seizure (2); glomerular disease (2); Graves disease (2); intraductal papillary mucinous neoplasm (2); macrophage activation syndrome (2); metastasis (2); multiple sclerosis (2); myeloproliferative neoplasm (2); neurodegenerative disease (2); obstructive sleep apnea (2); oligodendroglioma (2).
A further 131 diseases each share a sentence with PTX3 in 2 papers or fewer.